LAG3 (lymphocyte activating 3)
Diseases named in the same sentence as LAG3 in open-access papers (continued):
Sharing a sentence is not in itself a finding about the gene and the disease.
melanoma (continued). "Since MHC II is known to interact with lymphocyte activation gene 3 (LAG3), an immune checkpoint inhibitor which is also present on primary NK‐cells, we sought to examine the direct impact of MHC II and LAG‐3 interaction in melanoma resistance to NKmK." (PMID 41078003, 2025). "Going forward, deeper mechanistic investigation will be needed to understand why dual PD1/LAG-3 blockade appears more effective in melanoma versus other tumor types." (PMID 40993242, 2025). "Dual PD-1/LAG-3 blockade has emerged as an effective melanoma therapy, but recent clinical experience and trial data indicate an associated rise in dermatologic toxicity." (PMID 41458837, 2025). "The introduction of monoclonal antibodies targeting cytotoxic T lymphocyte antigen-4 (CTLA-4), program death protein 1 (PD-1), or lymphocyte activation gene-3 (LAG-3) dramatically changed the prognosis of patients with late-stage melanoma." (PMID 40507314, 2025). "Using animal models of melanoma, Dario A.A. Vignali's group conducted single‐cell RNA sequencing (scRNA‐seq) and discovered that CD8+T cells deficient in both PD‐1 and LAG‐3 exhibited a wide diverse array of TCR clones at the transcriptional level." (PMID 40415479, 2025). "Recently, the third clinically relevant immune checkpoint inhibitor blocking the lymphocyte activation gene-3 (LAG-3) was approved for melanoma treatment." (PMID 40507314, 2025). "In tumor-infiltrating NK cells from non-small-cell lung cancer and melanoma, a similar upregulation of LAG-3 was observed." (PMID 40805205, 2025). "Newer ICIs such as relatlimab, which target lymphocyte-activating gene 3 (LAG-3), are also gaining popularity for the treatment of advanced melanoma." (PMID 40673289, 2025). "For instance, relatlimab, an anti-LAG-3 antibody, has demonstrated clinical benefit in combination with nivolumab in melanoma and is currently under investigation for HCC." (PMID 41013723, 2025). "The co‐inhibitory receptors PD‐1, TIM‐3, and LAG‐3 are frequently co‐expressed on senescent CD8+ T cells in the melanoma microenvironment of aged individuals." (PMID 40926366, 2025). "A phase I trial of Fianlimab (LAG-3 inhibitor) in combination with cemiplimab in melanoma patients showed favorable response (NCT03005782)." (PMID 40236693, 2025). "Given the effectiveness of anti-LAG-3 in melanoma, there is a growing need for additional clinical trials to explore the combination of anti-PD-1/PD-L1 and anti-LAG-3 in different cancer types." (PMID 39751894, 2025). "For example, the RELATIVITY-047 trial evaluating nivolumab plus the LAG-3 inhibitor relatlimab has shown promise in melanoma, and similar combinations are now being explored in HNSCC." (PMID 41179287, 2025). "The RELATIVITY-047 trial showed that the combined use of a LAG3 inhibitor and nivolumab had remarkable efficacy in untreated advanced melanomas." (PMID 40329678, 2025). "Opdualag, the combination of anti-PD-1 (nivolumab) and anti-LAG-3 (relatlimab) antibodies has demonstrated clinical efficacy in melanoma." (PMID 39751894, 2025). "Among these, LAG-3 has attracted particular attention after the approval of NIVO plus relatlimab (anti–LAG-3) for melanoma and the launch of multiple trials in other solid malignancies." (PMID 41463268, 2025). "The success of this combination in melanoma likely reflects the significant role of LAG-3 as a coinhibitory receptor contributing to T-cell exhaustion in a substantial proportion of these patients." (PMID 40508202, 2025). "Several studies have shown the presence of a LAG-3-positive lymphocytic infiltrate in melanoma, laying the basis of a new therapeutic approach aimed at LAG-3/MCH-II binding inhibition." (PMID 39086722, 2024). "This trial aims to offer further verification of the effectiveness of utilizing the combination of LAG-3 and PD-1 in the treatment of melanoma." (PMID 39252941, 2024). "Previous studies have confirmed that melanoma patients with LAG3+CD8+ immunotype have worse prognosis after immunotherapy." (PMID 38213728, 2024).
melanoma (continued). "In preclinical melanoma models, interrupting T cell immunity can be achieved through the interaction between LAG-3 and LSECtin." (PMID 38390331, 2024). "In the phase II-III, double-blind, randomized RELATIVITY-047 trial, relatlimab (anti-LAG-3) and nivolumab as a fixed dose, compared with nivolumab alone, was evaluated in melanoma patients with unresectable or metastatic disease." (PMID 39727691, 2024). "The collaboration of relatlimab, an anti-LAG-3 antibody, with nivolumab, a PD-1 inhibitor, represents a significant step forward in the treatment of melanoma." (PMID 38474231, 2024). "We observed heightened efficacy of a combined CPMV IIT and anti-LAG-3 treatment in a mouse model of melanoma." (PMID 38349406, 2024). "LAG-3 (lymphocyte-activation gene 3) inhibitors have become a significant development in melanoma immunotherapy, especially when used in combination with PD-1 inhibitors." (PMID 38474231, 2024). "The most recent ICI to be approved for adjuvant treatment of melanoma is relatimab, a LAG-3 inhibitor that acts upon a co-inhibitory T-cell receptor that suppresses T-cell activation." (PMID 39123418, 2024). "Recent approval for Lymphocyte-activation gene 3 (LAG-3) targeting ICI therapy in melanoma has increased the range of approved ICI treatments." (PMID 38647024, 2024). "Consistently, a combination of PD-1 and LAG-3 blockade has been shown to promote an antitumor immune response in vitro and in vivo in several tumors, including melanoma, renal carcinoma, and CLL." (PMID 39425148, 2024). "Overall, the results of the RELATIVITY‐047 trial demonstrate that co‐blockade of LAG‐3 and PD‐1 is an effective therapeutic strategy in melanoma and inaugurate LAG‐3 as the third T cell inhibitory pathway whose blockade is beneficial in the clinics." (PMID 39560030, 2024). "Efficacy of the CPMV IIT + anti-LAG-3 ICT combination was investigated against a dermal B16F10 melanoma mouse model (C67BL/6 J) mice." (PMID 38349406, 2024). "The combination of anti-PD1 and anti-LAG-3 showed promising results in the treatment of advanced melanoma." (PMID 38610925, 2024). "LSECtin, expressed in melanoma, interacts with LAG-3 to inhibit IFN-γ secretion by effector T cells, thus promoting tumor growth." (PMID 39252941, 2024). "A significant study involving large cohorts of stage III or IV melanoma patients found that pairing anti-LAG3 antibodies with anti-PD-1 antibodies considerably enhanced progression-free survival compared to using anti-PD-1 antibodies alone." (PMID 38592036, 2024). "The PD-1 × LAG-3 ICI combination therapies have been shown improve PFS compared to PD-1 Mabs in melanoma." (PMID 38627681, 2024). "The therapeutic combination of relatlimab (BMS-986,016, a LAG-3 inhibitor) and nivolumab (a PD-1 inhibitor) is also being investigated in patients with melanoma." (PMID 38627681, 2024). "Especially noteworthy is the combination of relatlimab (anti-LAG-3) and nivolumab (anti-PD-1), which has shown promising preliminary efficacy in melanoma patients previously unresponsive to anti-PD-1/PD-L1 therapy (NCT01968109)." (PMID 38375475, 2024). "Comparative analyses between LAG-3 inhibitors and other emerging therapies provide valuable insights into their positioning within the current melanoma treatment landscape." (PMID 39743998, 2024). "Lymphocyte-activation gene 3 (LAG-3) is an immune checkpoint protein that inhibits T cell activity and is upregulated in various tumor types, including melanoma." (PMID 39234260, 2024). "The current trending themes include LAG-3 inhibitor (#0), neck cancer (#1), advanced melanoma (#4), T cell (#8), and renal clear cell carcinoma (#10), and it is expected that they will remain popular in the future." (PMID 38390331, 2024). "For example, in vitro studies have shown that inhibition of LAG-3 signaling in TILs from patients with melanoma restores the ability of CD4+ and CD8+ T cells to secrete IFN-γ, thereby enhancing their antitumor activity." (PMID 39660130, 2024).
melanoma (continued). "In another study, fianlimab (REGN3767, anti-LAG-3) and cemiplimab (anti-PD-1) were assessed in patients with melanoma and showed an acceptable safety profile and some clinical activity (NCT03005782)." (PMID 38581716, 2024). "In a phase 2–3 trial, researchers evaluated relatlimab (anti-LAG-3) and nivolumab (anti-PD-1) as a fixed-dose combination in patients with previously untreated metastatic or unresectable melanoma." (PMID 38581716, 2024). "Elevated levels of LAG-3 in T cells have the potential to shield melanoma cells and impede the apoptosis of tumor cells." (PMID 39534873, 2024). "The fully human IgG4 fianlimab (REGN3767), which is another LAG-3 inhibitor, has been utilized in combination with cemiplimab (PD-1 inhibitor) in patients with advanced melanoma." (PMID 39086722, 2024). "More recently, other checkpoints have gained interest, including lymphocyte activation gene 3 (LAG-3), which is targeted with relatlimab and is now approved to treat advanced melanoma in combination with nivolumab." (PMID 39766048, 2024). "This review discusses the latest advancements in LAG-3 inhibition for advanced melanoma, emphasizing its role in overcoming resistance and improving patient outcomes." (PMID 39743998, 2024). "Antibodies against LAG-3 have been successfully used in melanoma patients, especially in combination with anti-PD-1 antibodies." (PMID 38275911, 2024). "In conclusion, while PD-1 inhibitors remain a cornerstone in melanoma therapy, the addition of LAG-3 inhibitors, either alone or in combination with other emerging treatments, represents a significant advancement." (PMID 39743998, 2024). "Current research is exploring anti-LAG-3 antibodies both alone and in combination with other immunotherapies for treating melanoma." (PMID 39290699, 2024). "The presence of LAG-3 has been detected in diverse cancer types, including breast cancer, melanoma, colorectal cancer, Hodgkin’s lymphoma, ovarian carcinoma, chronic lymphocytic leukemia, multiple myeloma, hepatocellular carcinoma, and gastric carcinoma." (PMID 38390331, 2024). "Melanoma patients who responded to the combination therapy of anti-LAG-3 and anti-PD-1 were found to have higher NK cell levels in the tumours and greater transcriptional changes associated with IFN-γ responses, cytotoxicity, and degranulation." (PMID 39337605, 2024). "For example, Retilimab, an antibody specifically targeting LAG-3, has been utilized with the PD-1 inhibitor nivolumab to treat metastatic or unresectable melanoma." (PMID 39343796, 2024). "In numerous solid tumors such as ovarian cancer, melanoma, colorectal cancer, and hematological malignancies, including Hodgkin and diffuse large B-cell lymphoma, TILs with elevated LAG-3 expression have been identified." (PMID 39343796, 2024). "In melanoma, the dual LAG-3 and PD-1 inhibitor Opdualag was already approved by the FDA for treating unresectable or metastatic disease in adults and children." (PMID 39769271, 2024). "In 2022, the US Food and Drug Administration (FDA) approved relatlimab (BMS-986016) as the first human IgG4 monoclonal antibody anti-LAG-3 for the treatment of several cancers, including melanoma." (PMID 39086722, 2024). "The LAG-3 inhibitor relatimab is the most recent immune checkpoint inhibitor approved for the adjuvant treatment of melanoma." (PMID 39123418, 2024). "This review will examine the latest developments in LAG-3 inhibition as a therapeutic strategy for advanced melanoma, exploring its potential to overcome resistance to existing ICIs and improve patient outcomes." (PMID 39743998, 2024). "Post-treatment analysis of biospecimens from patients with advanced melanoma demonstrated that dual blockade of LAG-3 and PD-1 leads to enhanced capacity for CD8+ T cell receptor signalling and cytotoxicity, despite the retention of an exhaustion profile." (PMID 39337605, 2024).
melanoma (continued). "Higher LAG-3 expression in melanoma correlated with longer progression-free survival (PFS) compared to tumors with less than 1% LAG-3 expression." (PMID 39404378, 2024). "As these challenges are addressed, LAG-3 inhibitors are expected to bring new breakthroughs in the treatment of melanoma and other malignancies, ultimately improving patient prognosis." (PMID 39743998, 2024). "Presently, immunotherapy targeting LAG3 is largely used for melanoma, pancreatic cancer, and hematological tumors, with only a few studies on renal cancer." (PMID 38291496, 2024). "Compared to LAG-3 blockade alone, the combination of LAG-3 and PD-1 inhibitors has shown a more promising response rate in patients with refractory melanoma." (PMID 39290699, 2024). "Our study brings also pertinent information for the next generation of ICP receptors being harnessed in the clinic especially in melanoma, such as LAG3, TIM3 and TIGIT." (PMID 39687620, 2024). "Within the tumor microenvironment, LAG-3 expression is markedly upregulated, particularly in advanced melanoma, where it acts on tumor-infiltrating CD4CD25 high FoxP3 Treg subsets." (PMID 39743998, 2024). "LAG3 is another biomarker for immunotherapy, and antagonists of LAG3 enhance the antitumor efficacy of PD-L1 blockade therapy in colon cancer and melanoma." (PMID 39052013, 2024). "Over 30 types of anti-LAG-3 antagonists have progressed to the clinical development and trial phase for treating hematological tumors, breast cancer, renal cell carcinoma, melanoma, colon cancer, and other tumors." (PMID 38390331, 2024). "LAG-3 interacts with the lectin LSECtin on B16 melanoma cells to inhibit effector T cell IFN-γ secretion." (PMID 38898505, 2024). "As a result, LAG-3 inhibitors are now being explored in clinical trials for the treatment of advanced melanoma and other cancers." (PMID 39743998, 2024). "Despite some promising studies conducted in recent years on the role of LAG3 in cancer, especially melanoma, there are still many unanswered questions, most of which are related to the action mechanism of LAG3." (PMID 38418707, 2024). "We therefore, investigated the combination of CPMV IIT and LAG-3 blockade to treat an aggressive and immunosuppressive mouse model of melanoma, B16F10." (PMID 38349406, 2024). "The effects of the combined use of PD-1 and LAG-3 antibodies were then summarized in animal models of melanoma, MC38 carcinoma, and other tumors." (PMID 38581716, 2024). "Ani-PD-1 has been used clinically for several cancers such as melanoma, lung and breast cancer, with evidence of anti-LAG-3 immunotherapeutic blockade efficacy emerging through numerous active cancer treatment clinical trials." (PMID 37344517, 2023). "The combination of LAG3 and PD-1 inhibitors (relatlimab and nivolumab) is more effective than nivolumab monotherapy as a first-line therapy for advanced melanoma." (PMID 38062416, 2023). "LAG-3 expression mediated immune escape in melanoma cells by impairing immune cell function while also protecting against Fas- and drug-induced apoptosis via its interaction with MHC-II." (PMID 37670328, 2023). "Further research is warranted to assess the cutaneous adverse events observed with the use of LAG‐3 inhibitors in treating melanoma and to identify populations most vulnerable to such side effects." (PMID 38047262, 2023). "LAG3 blockade therapies have been shown to have therapeutic benefit for patients with chronic lymphocytic leukemia, melanoma, and pancreatic adenocarcinoma." (PMID 38086828, 2023). "In melanoma, LAG-3/MHC-II interaction was shown to mediate TLR-independent induction of tolerogenic human pDCs in TME in vivo, maintaining immunosuppression." (PMID 37345056, 2023). "LAG3 inhibition for treating metastatic or unresectable melanoma has a reduced efficacy in patients with type 2 diabetes, possibly due to a low expression of LAG3 in tumor tissue." (PMID 37880788, 2023).
melanoma (continued). "Relatlimab targeting the lymphocyte-activation gene 3 (LAG-3) received its first approval by the FDA for the treatment of metastatic or unresectable melanoma in March 2022." (PMID 37386520, 2023). "The synergistic effect between LAG-3 and PD-1 has been described in murine melanoma, colorectal adenocarcinoma, and fibrosarcoma models where the dual blockade of both PD-1 and LAG-3 resulted in tumor eradication and prolonged survival in mice." (PMID 37509517, 2023). "It was shown that LAG-3/MHC-II signaling in melanoma cells prevents their apoptosis by activating MAPK/ErK and PI3K/Akt survival pathways." (PMID 37509517, 2023). "The phase II/III RELATIVITY-047 trial led to the momentous FDA approval of relatlimab (anti-LAG-3) in combination with nivolumab in untreated advanced melanoma patients." (PMID 37520544, 2023). "Coinhibition of anti–LAG-3+anti–PD-1 is more attractive than blocking either LAG-3 or PD-1 alone, with encouraging efficacy even in patients with anti–PD-1/anti–PD-L1–refractory melanoma." (PMID 36719749, 2023). "LAG3 was identified as an important therapeutic target in pancreatic cancer, liver, brain, breast cancer and melanoma." (PMID 37608927, 2023). "LAG-3 is overexpressed in many tumors, including melanoma, gastric, ovarian, anal and colorectal, hepatocellular, prostate, follicular, breast, head and neck, NSCLC, renal, pancreatic, and mesothelioma cancer." (PMID 36829496, 2023). "The reduced toxicity with similar outcomes shown with this treatment suggests a possible important role for anti-LAG-3-based combination in the treatment of melanoma patients, but data on OS are still immature." (PMID 38201531, 2023). "Recently, the FDA approved the use of Relatlimab, an anti-LAG-3 monoclonal antibody, in combination with Nivolumab for the first-line treatment of advanced melanoma." (PMID 36768978, 2023). "The anti-LAG-3 drug relatlimab in combination with nivolumab has already proven its efficacy in patients with malignant melanoma in a phase 2–3 trial and is more effective than nivolumab monotherapy." (PMID 36980787, 2023). "Interaction between LAG-3 and LSECtin in melanoma cells has been found to impede IFNγ production by antigen-specific effector T cells, thereby altering the tumor microenvironment." (PMID 37569880, 2023). "Optimistic findings for the success of anti-LAG-3 as a complementary partner to PD-1 blockade has been reported in melanoma patients." (PMID 37520544, 2023). "A combined anti-PD-1/anti-LAG-3 therapy has already been approved for the treatment of melanoma patients." (PMID 37174080, 2023). "This indicates preserved proinflammatory potential of DP cells and is supported by transcriptomic data in circulating PD-1+TIGIT+ CD8+ T cells, mostly co-expressing LAG-3, in melanoma and Merkel cell carcinoma." (PMID 37794264, 2023). "Further research is warranted to assess the cutaneous adverse events observed with LAG‐3 inhibitors in treating melanoma and to identify populations most vulnerable to such side effects." (PMID 38047262, 2023). "To evaluate the impact of diabetes on oncological outcomes of patients with advanced melanoma treated with nivolumab plus the LAG3 inhibitor relatlimab we performed a retrospective multicenter study." (PMID 37880788, 2023). "Recent clinical studies have looked at LAG‐3 inhibitors as a promising treatment for cancers, including melanoma." (PMID 38047262, 2023). "Co-inhibition of PD-1 and CTLA-4 has an antitumor effect in patients with OCCC, but with severe adverse events; however, a randomized phase III study on melanoma revealed that co-inhibition of PD-1 and LAG-3 leads to favorable outcomes." (PMID 37179337, 2023). "Lymphocyte activation gene-3 (LAG-3), which is a co-inhibitory receptor on T cells that suppress their activation, has revolutionized immunomodulation in melanoma." (PMID 37484526, 2023).